LGALS9 (galectin 9)
Diseases named in the same sentence as LGALS9 in open-access papers (continued):
Sharing a sentence is not in itself a finding about the gene and the disease.
endometritis (1 paper, 2021). An acute or chronic, usually bacterial infectious process affecting the endometrium. "The compilation of the research results has demonstrated the potential of Bta-miR-24-3p in regulating the LPS-induced bovine endometritis through attenuation of TLR4/NF-ĸB cellular signaling pathway by targeting LGALS9." (PMID 34943807, 2021). "In conclusion, for the first time, this study revealed the cellular and molecular regulatory function of Bta-miR-24-3p against endometritis by targeting the LGALS9 gene." (PMID 34943807, 2021). "Overexpression of LGALS9 was reported in LPS-stimulated endometritis, depicting its role in the pathophysiology of bovine endometritis." (PMID 34943807, 2021). "LGALS9 is an endometrial gene found to incriminate in the pathogenesis of endometritis, leading to some other reproductive problems." (PMID 34943807, 2021). "It recognized that Bta-miR-24-3p regulates LPS-triggered endometritis by suppressing the TLR4/NF-ĸB signaling pathway by targeting the LGALS9 gene." (PMID 34943807, 2021). "We hypothesized that Bta-miR-24-3p has an immunomodulatory effect on LPS-induced endometritis through TLR4/NF-ĸB signaling pathway targeting LGALS9." (PMID 34943807, 2021). "Likewise, LGALS9 was earlier reported as a significant gene that was highly upregulated in LPS-induced endometritis." (PMID 34943807, 2021). "The need to regulate the expression of LGALS9 during the window of implantation and in normal early decidual was essential in embryonic development; therefore, there is a need to curb premature embryonic death as the result of endometritis." (PMID 34943807, 2021). "The need to knock down the expression of LGALS9 in BEECs could portray a point biomarker as molecular therapeutic regulation of endometritis." (PMID 34943807, 2021). "This study revealed that upon stimulation of BEECs with LPS, there was an elevation in the expression level of LGALS9 with a corresponding decrease in the level of Bta-miR-24-3p, indicating the alternate role of both in the molecular pathogenesis of endometritis." (PMID 34943807, 2021). "LGALS9 expression was significantly increased, and Bta-miR-24-3p was significantly downregulated; therefore, it affirmed that both LGALS9 gene and Bta-miR-24-3p are incriminated immune-inflammatory responses during endometritis." (PMID 34943807, 2021). "Additionally, recombinant cloning of LGALS9 into BEECs experiments confirmed that downward regulation of LGALS9 could enhance the therapeutic effect of Bta-miR-24-3p on LPS-induced endometritis, indicating that Bta-miR-24-3p could regulate endometritis progression by downregulating LGALS9." (PMID 34943807, 2021).
endothelial dysfunction (1 paper, 2022). In vascular diseases, endothelial dysfunction is a systemic pathological state of the endothelium (the inner lining of blood vessels) and can be broadly defined as an imbalance between vasodilating and vasoconstricting substances produced by (or acting on) the endothelium. "Specifically, we identified CCRL2, LGALS9, and PLCB2 as key genes associated with abnormal ESS and AS and initially explored the roles of these genes in endothelial dysfunction and AS, thus highlighting the possibility of new preventive and therapeutic strategies for AS by targeting these genes." (PMID 35990248, 2022).
Ewing sarcoma (1 paper, 2021). A small round cell tumor that lacks morphologic, immunohistochemical, and electron microscopic evidence of neuroectodermal differentiation. "Although expression of TIM-3 and Galectin 9 were seen on most Ewing sarcoma diagnostic biopsy samples, expression of TIM-3 on peripheral T cells at diagnosis was similar to other tumor types." (PMID 35938052, 2021). "We examined the immunohistochemical expression of checkpoint receptors PD-1, TIM-3, LAG-3 and their respective ligands in various pediatric cancers at diagnosis and found high expression of TIM-3/Galectin-9 in the infiltrating cells of Ewing sarcoma." (PMID 35938052, 2021). "First, both TIM-3 and Galectin 9 were highly expressed on non-tumor cells in Ewing sarcoma samples at diagnosis." (PMID 35938052, 2021). "For Ewing sarcoma, 4 of 10 (40%) samples had positive PD-1 staining of tumor cells, and 10 of 10 (100%) samples had positive staining for both TIM-3 and Galectin-9 in infiltrating non-tumor cells." (PMID 35938052, 2021).
gingivitis (1 paper, 2023). A disorder involving inflammation of the gums; may affect surrounding and supporting structures of the teeth. "The highest galectin-3 and galectin-9 levels were observed in the gingivitis group (p < 0.05)." (PMID 37809904, 2023).
HIV-associated neurocognitive disorder (1 paper, 2024). HIV-associated neurocognitive disorder (HAND) remains a common complication of HIV infection in the combination antiretroviral therapy (ART) era. "Further, in the SIV-macaque model of HIV-associated CVD and HIV-associated neurocognitive disorder (HAND), plasma IL-18, in addition to galectin-3 and galectin-9, was shown to correlate strongly with monocyte activation and turnover." (PMID 39201388, 2024).
inverted papilloma (1 paper, 2014). An endophytic benign papillary epithelial neoplasm that results from the invagination and proliferation of epithelial cells in the underlying stroma. "Indeed, epithelial overexpression of galectin-3 (P=0.0002), galectin-4 (P<10−6), galectin-7 (P<10−6) and galectin-9 (P<10−6) was observed in inverted papillomas compared to non-malignant diseases." (PMID 24859692, 2014).
low grade glioma (1 paper, 2020). A grade I or grade II glioma arising from the central nervous system. "In contrast, the expression of LGALS9 was lower in low-grade glioma (LGG)." (PMID 33093453, 2020).
mastitis (1 paper, 2024). Inflammation of breast tissue during lactation or postpartum due to an obstructed duct or infection. "The targeted genes, PLIN3, EDEM2, SURF4, and LGALS9, with mutations/variations have led to metabolic diseases, bovine osteoporosis, mastitis resistance and bovine respiratory disease, respectively." (PMID 38674383, 2024).
neuroendocrine tumors (1 paper, 2021). "Other immune checkpoint ligand molecules, such as CTLA-4, galectin-9 and CD155, have been investigated in some neuroendocrine tumors and their expression has been associated with better prognosis and response to immune checkpoint inhibitors." (PMID 34208144, 2021).
papillary thyroid carcinomas (1 paper, 2021). "Therefore, the gene expression levels of TIM3 and galectin 9 were analyzed in papillary thyroid carcinomas (PTCs, n = 502) and normal tissue (n = 57) from The Cancer Genome Atlas (TCGA) datasets." (PMID 34638305, 2021).
paraganglioma (1 paper, 2025). A benign or malignant neoplasm arising from paraganglia located along the sympathetic or parasympathetic nerves. "Beyond the common increased IL6 and sB7.2 expression levels displayed by both tumor entities compared to HVs, pheochromocytomas showed heightened MCP1, sPD-L1 and sCD25 levels, while paragangliomas exhibited reduced sPD-L2 expression with increased levels of sLAG3 and Galectin-9." (PMID 40038821, 2025).
pneumococcal meningitis (1 paper, 2014). An acute purulent infection of the meninges and subarachnoid space caused by Streptococcus pneumoniae, most prevalent in children and adults over the age of 60. "While galectin-9 is minimally expressed in the unchallenged brain, its expression has been reported to increase following acute infection with herpes simplex virus and during pneumococcal meningitis indicating that CNS infection likely promotes galectin-9 up-regulation." (PMID 25158758, 2014).
Psoriasiform dermatitis (1 paper, 2025). A skin abnormality characterized by redness and irritation, with thick, red skin that displays flaky, silver-white patches (scales). "Pharmacological restoration of the axis also has a proof-of-concept: a stable form of galectin-9 (a TIM3 ligand) suppresses contact hypersensitivity and IL-23–driven psoriasiform dermatitis, reducing IL-17/IL-22 and epidermal STAT3 activation." (PMID 41307843, 2025).
salivary gland carcinoma (1 paper, 2020). A carcinoma that arises from the major or minor salivary glands. "These were the PD-1/PD-L1 interaction, that has already been evaluated in SDCs 16 and tested in advanced salivary gland carcinomas 14, as well as the CTLA-4/DC86 and TIM-3/galectin-9 interactions." (PMID 32292502, 2020).
spinal chordoma (1 paper, 2021). A slow-growing malignant bone tumor arising from the remnants of the notochord and occurring in the spine. "Here, we aimed to determine the expression of PD-L1, HHLA2, B7H3, IDO-1 and Galectin-9 in spinal chordoma and evaluated their association with tumor infiltrating lymphocytes (TILs), clinicopathological characteristics and survival of patients." (PMID 35145510, 2021). "In this study, we objectively analyzed the expression and coexpression of PD-L1, HHLA2, B7H3, IDO-1 and galectin-9 in spinal chordoma tissues and investigated the clinical impact of these immune checkpoints." (PMID 35145510, 2021). "In this study, we sought to objectively measure the expression of PD-L1, HHLA2, B7H3, IDO-1 and Galectin-9 in spinal chordoma tissues by multiplexed quantitative immunofluorescence (QIF)." (PMID 35145510, 2021). "The present study objectively measured the tumoral and stromal expression of PD-L1, HHLA2, B7H3, IDO-1 and Galectin-9 in spinal chordoma tissues and analyzed their relationship with the clinical data of patients." (PMID 35145510, 2021).
stomach adenocarcinoma (1 paper, 2025). "We performed bioinformatic analysis of The Cancer Genome Atlas (TCGA) stomach adenocarcinoma (STAD) dataset to assess LGALS9 and HAVCR2 expression and their clinical correlations." (PMID 40666515, 2025).
testicular germ cell tumor (1 paper, 2023). A germ cell tumor arising from the testis. "Furthermore, recent data indicates a correlation between AhR expression and immune inhibitors including colony-stimulating factor 1 receptor (CSF1R) and galectin 9 (LGALS9) in uterine carcinosarcoma and IL10RB in testicular germ cell tumors." (PMID 37241719, 2023).
tularemia (1 paper, 2015). Tularemia is an infection caused by the bacterium Francisella tularensis. "In order to assess the role of galectin-9 in overall disease severity during tularemia, we next examined H&E stained lung cryosections from F.n. infected wild-type (WT) and Gal-9-/- mice." (PMID 25898318, 2015). "To examine the direct effect of galectin-9 on activation of neutrophils and macrophages, two cell types playing a predominant role in tularemia pathogenesis, we next carried out in vitro stimulation of these cells with recombinant galectin-9 protein with or without F.n. infection." (PMID 25898318, 2015).
vulvar cancers (1 paper, 2025). "The expression of TIM-3 and its ligand, Galectin-9, has been identified in various malignancies, including cervical and vulvar cancers, indicating a potential role for TIM-3 checkpoint inhibition in combination with anti-PD-1/PD-L1 therapies." (PMID 40458414, 2025).
tumor (548 papers, 2006 to 2026). "Hmgb1/HMGB1 is expressed by ccRCC cells and myeloid cells in mouse and human tumours and Lgals9/LGALS9, encoding GALECTIN-9 is expressed by myeloid cells in both mouse and human ccRCC." (PMID 40473819, 2025). "By exploring published scRNA-seq data of these two cancer types, we observed LGALS9 expression mainly in tumor-associated myeloid cells." (PMID 40775219, 2025). "In solid cancers however, galectin-9 is likely produced mainly by myeloid cells, like tumor-associated macrophages or myeloid-derived suppressor cells." (PMID 40775219, 2025). "Galectin-9, a tandem-repeat β-galactoside-binding lectin encoded by LGALS9, has emerged as a multifaceted regulator with significant roles in both tumor biology and immune modulation." (PMID 40710343, 2025). "Given LGALS9 upregulation in immune-hot tumors, we assessed tumor-associated macrophages via CD68 (pan-macrophage marker) and CD163 (M2 macrophage marker) IHC to evaluate their contribution to an immunosuppressive microenvironment." (PMID 41332664, 2025). "Further mechanistic insights revealed that this phagocytic capacity depends on the formation of a bridging complex involving erythroid membrane-associated protein (ERMAP) expressed on tumor cells and galectin-9 on Kupffer cells." (PMID 41163402, 2025). "In many solid tumors, higher galectin-9 expression has been associated with lower tumor progression and better overall and progression-free survival." (PMID 39000016, 2024). "The retained approach was to reverse the tumor immunosuppression of M2-like tumor-associated macrophages through disruption of the dectin 1/galectin-9 axis." (PMID 38607173, 2024). "In the precise case of galectin-9, expression can be up or downregulated in association with neoplastic transformation depending on the specific tumor type." (PMID 38697976, 2024). "Upon TMZ treatment, Galectin signaling was linked to Lgals9 produced by myeloid cells predicted to interact with Cd44 in tumor cells and Ptprc (Cd45) in ependymal and myeloid cells." (PMID 38566128, 2024). "Galectin-9 expression also regulates macrophage M1/M2 polarization, while tumor-associated macrophages are generally M2-like and facilitate tumor growth via induction of immune suppression in various tumors." (PMID 37047155, 2023). "The most widely studied of the four TIM-3 ligands is galectin-9 (gal-9), which causes the apoptosis of Th1 cells and is essential to tumor cell immune evasion." (PMID 37894427, 2023). "TIM-3 and LGALS9 gene polymorphisms, as well as gender, age, stage of disease, size of tumor, and the absence or presence of metastasis as well as necrosis were subjected to an OS analysis." (PMID 36768365, 2023). "The function of galectin-9 is strongly associated with tumor-immune microenvironment and immunosuppression in different cancer types." (PMID 36873388, 2023). "Although the galectin-9 expression is associated with a good prognosis in some cancers, it is associated with unfavorable outcomes in other tumor types." (PMID 36873388, 2023). "Treatment with this combined formulation in mice improved pancreatic ductal adenocarcinoma (PDAC) immunotherapy and reversed tumor immunosuppression of M2-like tumor-associated macrophages by disrupting the galectin-9/dectin-1 axis." (PMID 36766698, 2023). "Recent reports have demonstrated that an exosome-based dual-delivery biosystem enhances PDAC immunotherapy and restores tumor immunosuppression in M2-like tumor-associated macrophages by disrupting the galectin-9/dectin-1 axis." (PMID 37047155, 2023). "The overexpression of LGALS9 is associated with the tumor development, metastasis and poor prognosis." (PMID 37945567, 2023). "In EAC, the protein hampers tumor progression which is in line with the observation in ESCC that high galectin-9 expression is associated with better overall survival." (PMID 36497271, 2022).
tumor (continued). "In conclusion, high-risk group seems like an immune-desert tumor with high level of LGALS9, PD-1, and PD-L1, which was consistent with the former result of LGALS9 inducing the positive regulation of immune tolerance." (PMID 36263183, 2022). "LGALS9 encodes an S-type lectin involved in cell adhesion, immune escape, angiogenesis and tumor metastasis." (PMID 36476645, 2022). "Galectin-9 (Gal-9) is a β-galactoside-binding galectin, and has been described for its role in cancer, as loss of Gal-9 is associated with tumor progression and metastasis." (PMID 35884427, 2022). "CLEC7A, which is highly expressed in M2-like tumor-associated macrophages, is linked to galectin 9, thus leading to tolerogenic macrophage programming and adaptive immunosuppression that contribute to tumor exacerbation." (PMID 35480896, 2022). "By comparison, blockade of the Tim-3/galectin-9 signaling pathway importantly increases the functionality of tumor-infiltrating Tim-3+ T cells and is negatively associated with the survival of patients with HCC." (PMID 34778306, 2021). "Further analyses showed that tumoral HHLA2 levels and stromal expression of several QIF markers (including PD-L1, B7H3 and Galectin-9) were associated with tumor phenotype, microenvironmental immunity level and clinical outcomes." (PMID 35145510, 2021). "In a tumor-bearing mouse model, it was difficult for LGALS9-deficient GBM cells to grow in the presence of a healthy immune system, but in immunodeficient mice, this phenomenon was eliminated." (PMID 33093453, 2020). "In contrast, the growth rate of subcutaneous tumors formed from GL-261nSMase2−/−, Rab27a−/−, or LGALS9−/− cells was much slower, and the survival times associated with these cells were also significantly longer than that of GL-261 WT tumor-bearing mice." (PMID 33093453, 2020). "In conclusion, we show that low tumor expression of PD-L1 and Galectin-9, as well as low CD8+TIL count, are associated with poor HCC-specific survival in patients with resected HCC." (PMID 28344887, 2017). "The effects of galectin-9 in tumors are complex which are implicated in several aspects including tumor cell adhesion, apoptosis and cell cycle, migration, and angiogenesis." (PMID 27028892, 2016). "Galectin-9 expression was positively associated with tumor size, Fuhrman grade, and necrosis and was an independent prognostic indicator for OS in ccRCC." (PMID 27259255, 2016). "The CT26 tumor cells secrete galectin-9 which causes apoptosis of tumor-infiltrating CD8+ T cells in the tumor microenvironment in our experiment." (PMID 26493689, 2015). "A targeted delivery system composed of a cationic liposome-encapsulated TGF-β siRNA combined with galectin-9 inhibitors disrupted adenosine-dependent inhibition by tumour-associated macrophages (TAMs), significantly increasing the tumour infiltration density of CAR-NK cells." (PMID 41429765, 2025). "Notably, CD44 serves as a receptor for LGALS9, with its expression in tumor and immune cells closely linked to tumor migration, invasion, and immune evasion." (PMID 40747615, 2025). "When engaged predominantly on TAMs and MDSCs, and triggered by ligands such as Galectin-9 or tumor-associated β-glucans, Dectin-1 signaling drives immunosuppressive reprogramming, leading to PGE2 and IL-1β production, T cell dysfunction, and resistance to checkpoint blockade." (PMID 41163402, 2025). "Furthermore, galectin-9 on γδ T cells and tumor cells drives the polarization of M2-like tumor-associated macrophages, which secrete immunosuppressive molecules that impede the antitumor activity of γδ T cells." (PMID 39748921, 2024). "Galectin 9 is associated with T cell exhaustion in the tumor environment." (PMID 38012322, 2023). "However, associations between the overexpression of galectin-9 in tumour tissues (immunohistochemistry (IHC) staining) and clinicopathological/survival parameters have been quite controversial in different studies." (PMID 37371482, 2023).